PRDX1 (peroxiredoxin 1)
Diseases named in the same sentence as PRDX1 in open-access papers (continued):
Sharing a sentence is not in itself a finding about the gene and the disease.
glioma (14 papers, 2014 to 2024). A benign or malignant brain and spinal cord tumor that arises from glial cells (astrocytes, oligodendrocytes, ependymal cells). "Firstly, we transfected PRDX1 overexpression plasmid into IRAK1-deficient glioma cells, which was verified by Western blotting." (PMID 37031183, 2023). "Ezrin is also shown to increasesecretion of other molecules in neutrophils.Peroxiredoxin 1, an antioxidant and molecularchaperone, is overexpressed in many cancersincluding gliomas and its elevation is associatedwith poor clinical outcome." (PMID 28670517, 2017). "A study in glioma demonstrated that high levels of IRAK1 bound to and prevented the degradation of PRDX1, a major member of antioxidant enzymes, in glioma cells, leading to the suppression of autophagic cell death and development of radioresistance." (PMID 39451208, 2024). "IRAK1 knockdown increased PRDX1 degradation, reduced malignancy, and enhanced radiosensitivity of glioma both in vitro and in vivo." (PMID 39451208, 2024). "Hypermethylation silenced the PRDX1 promoter and sensitized brain tumors to temozolomide and ionizing radiation PRDX1 overexpression in glioma cells enhanced resistance to bis-chloroethyl nitrosurea (BCNU)." (PMID 36839749, 2023). "Taken together, these results suggested that IRAK1 promotes the radioresistance of glioma cells by PRDX1-mediated suppression of autophagic cell death." (PMID 37031183, 2023). "Consistently, the detection of autophagy flux indicated by the formation of LC3B puncta revealed that the autophagy level was significantly increased in glioma cells with PRDX1 knockdown and decreased in cells with PRDX1 overexpression." (PMID 37031183, 2023). "The reduced phosphorylation levels of Akt and mTOR in IRAK1 depletion glioma cells were restored by PRDX1 overexpression, ATG5 knockdown or 3-MA treatment." (PMID 37031183, 2023). "The silencing of PRDX1 increases the chemo- and radiosensitivity of glioma cells in vitro, while also prolonging survival in mouse glioma models." (PMID 37566013, 2023). "The functions of a series of E3 ubiquitin ligases have been reported in glioma, for instance, radiation induces E3 ligase IRAK1 expression to promote radioresistance of glioma by decreasing the ubiquitination of PRDX1 and suppressing autophagy." (PMID 37723588, 2023). "Peroxiredoxin antioxidants are increased in various solid tumours and PRDX1 is up-regulated in GBMs compared to low-grade gliomas." (PMID 24728830, 2014). "Having proved that PRDX1 is involved in inhibiting the formation of autophagosomes, we then evaluated whether such regulation is the key mechanism for PRDX1’s impact on the radiosensitivity of glioma cells." (PMID 37031183, 2023). "Moreover, PRDX1 enhanced in vivo glioma brain invasion, but reducing its expression increased survival in mouse glioma models." (PMID 34055785, 2021). "PRDX1 stimulated infiltrative growth of IDH-wild-type gliomas." (PMID 34055785, 2021). "As for its expression pattern in different glioma subtypes, PRDX1 may be connected to the poor prognosis of glioma subtypes, including glioblastoma and astrocytoma." (PMID 30322114, 2018). "Thus, we next investigated the effect of PRDX1 on autophagy in glioma cells." (PMID 37031183, 2023). "In addition, the expression pattern of PRDX1 may be a potential biomarker for the recognition of astrocytoma in elderly patients, confirming its potential role in the differential diagnosis of glioma." (PMID 30322114, 2018). "In particular, overexpression of PRDX1, PRDX4, and PRDX6 has been reported in most histological glioma types compared to the normal tissues and correlated with poor survival of glioma patients." (PMID 38607010, 2024). "We then treated glioma cells with the proteasome inhibitor MG132 and found that IRAK1 silencing-mediated destabilization of PRDX1 was reversed by MG132." (PMID 37031183, 2023).
glioma (continued). "Specifically, PRDX1 forms a heterodimer with p38α MAPK14, stabilizing phospho-p38α in glioma cells and enhancing HGF-mediated signaling." (PMID 34055785, 2021). "Together, all these results suggested that the radioresistance of glioma cells is impaired by IRAK1 knockdown, which could be reversed by overexpression of PRDX1." (PMID 37031183, 2023).
ovarian carcinoma (13 papers, 2011 to 2025). A malignant neoplasm originating from the surface ovarian epithelium. "In our ovarian cancer cohort, high PRDX1 was associated with poor survival and worse outcomes for ovarian cancer patients in line with findings from other clinical studies." (PMID 40387816, 2025). "In a proteomics study, overexpression of PRDX1 was significantly associated with poor prognosis in ovarian cancer." (PMID 37501157, 2023). "High mRNA expression of PRDX1 showed a null association with OS or PFS among all ovarian cancer patients, serous ovarian cancer patients, and endometrioid ovarian cancer patients." (PMID 30104402, 2018). "PRDX1 has been identified as overexpressed in various subtypes of ovarian carcinoma and is implicated in the promotion and support of transformed tumor cells." (PMID 28250404, 2013). "Analysis of a clinical cohort of ovarian cancers treated with platinum chemotherapy revealed that tumours with high PRDX1/high ATM or high PRDX1/high MRE11 expression manifested aggressive phenotypes and poor patient survival." (PMID 40387816, 2025). "The clinical data suggest that high PRDX1 is a predictor of response to platinum chemotherapy and poor prognosis in ovarian cancer." (PMID 40387816, 2025). "Ovarian cancers with high PRDX1/high ATM or high PRDX1/high MRE11 expression showed poor survival and an aggressive phenotype." (PMID 40387816, 2025). "PRDXs constitute a large superfamily (PRDX1–6) of proteins that are involved in the processes of inflammation and tumor development, including ovarian cancer." (PMID 35668784, 2022). "Taken together, the prognostic value of PRDX1 in ovarian cancer remains controversial and requires further study." (PMID 30104402, 2018). "Analysis indicated that a high expression of PRDX1 was correlated with a better OS in grade I or II ovarian cancer patients." (PMID 30104402, 2018). "In comparison, among 12 cases of ovarian cancer tissues examined, medium staining of PRDX1 was detected in the majority of cancerous tissues (ten cases), while the rest two cases had low PRDX1 staining." (PMID 30104402, 2018). "They observed that PRDX1 was overexpressed in most malignant ovarian tumors and was correlated with a poorer overall survival rate in patients suffering from ovarian serous cancer." (PMID 30104402, 2018). "We limited this external validation of PRDX1 to serum because elevated levels of PRDX1 have already been demonstrated in ovarian cancer tissue by western blot and immunohistochemistry." (PMID 21980378, 2011). "Hence, the nominated combinations are beneficial in overcoming drug resistance in ovarian cancer involved abnormal expression of PRDX1." (PMID 33053689, 2020). "In addition to these discrepancies, studies about the prognosis of PRDX1 in ovarian cancer are limited." (PMID 30104402, 2018). "However, the clinical stage results showed that high levels of PRDX1 mRNA were associated with a poorer PFS in stages I and II ovarian cancer patients." (PMID 30104402, 2018). "In addition, PRDX1 also predicted a better PFS in grade I ovarian cancer patients." (PMID 30104402, 2018). "The expression of PRDX1, ATM, and MRE11 were investigated using Tissue MicroArrays (TMA) of 331 consecutive ovarian epithelial cancer cases treated at Nottingham University Hospitals (NUH) between 1997 and 2010." (PMID 40387816, 2025). "In the present study, the presence of PRDX1 in TIF and ascites from ovarian cancer patients was verified by western blot to be elevated in abundance in TIF as compared to ascites." (PMID 21980378, 2011). "Together the data support the hypothesis that PRDX1 interaction with ATM and the MRN components could influence patients’ prognosis in ovarian cancers." (PMID 40387816, 2025). "Both PRDX1 and ANXA2 are elevated in stage I endometrial cancer, and ANXA2 has been suggested as a potential biomarker for recurrent endometrial cancer and in ovarian cancer progression (regulation of β-catenin-driven epithelial-mesenchymal transition)." (PMID 32106990, 2020).
ovarian carcinoma (continued). "However, the prognostic value of PRDX1, PRDX2, and PRDX4 in ovarian cancer requires further exploration." (PMID 30104402, 2018). "However, the use of PRDX1, PRDX2, and PRDX4 as a prognostic indicator in ovarian cancer needs further study." (PMID 30104402, 2018). "Furthermore, increased PRDX1 mRNA expression was not correlated with OS or PFS among all ovarian cancer patients treated with Platin, Taxol, and Taxol+Platin chemotherapy." (PMID 30104402, 2018).
gastric cancer (12 papers, 2014 to 2025). A primary or metastatic malignant neoplasm involving the stomach. "It is possible that gastric cancer patients expressing reduced levels of PRDX1 are associated with poor outcome due to the induction of a proinflammatory response." (PMID 27388124, 2016). "Thus, the high expression of PRDX1 associated with some types of cancers, such as we show herein for gastric cancer might be to reduce inflammation." (PMID 27388124, 2016). "High PRDX1 expression positively correlates with lymph node invasion and unfavorable prognosis, making PRDX1 a potential therapeutic and prognostic target for gastric cancer patients 48-50." (PMID 37781072, 2023).
lymphoma (12 papers, 2015 to 2025). A malignant (clonal) proliferation of B- lymphocytes or T- lymphocytes which involves the lymph nodes, bone marrow and/or extranodal sites. "Prdx1-knockout mice (Prdx1−/−) develop an age-related haemolytic anaemia, linked to higher levels of ROS in erythrocytes and various types of malignancies (lymphomas, sarcomas and carcinomas) associated with increased ROS-dependent DNA damage and functional c-Myc deregulation." (PMID 34215320, 2021). "A previous study showed that PRDX1 knockout mice developed severe hemolytic anemia and several malignant cancers, including lymphomas, which shortened their life span." (PMID 34353368, 2021). "Loss of expression of B2M, and gain of expression of PRDX1 and PPIA was confirmed in the cell lines and primary lymphoma tissue." (PMID 26752561, 2016). "In vivo, PRDX1 knockout mice developed several malignancies, including lymphomas and sarcomas." (PMID 36969053, 2023). "The lymphoma character of Ramos B cells was reflected by the abundance of cancer-associated proteins including the heat shock protein 90, the cytokine macrophage migration inhibitory factor MIF, glutathione S-transferase P and peroxiredoxin-1." (PMID 34526379, 2021). "Considering the accumulation of covalent PRDX1 dimers upon SK053 in lymphoma cells, we speculated that the two catalytic Cys residues, Cys52 and Cys173, are both binding sites of SK053." (PMID 26636537, 2016). "Notably, PRDX1 expression was seen increased upon B cell activation and was high in lymphomas." (PMID 26636537, 2016). "Particularly, we show that PRDX1 and PRDX2 are abundantly expressed in B cell-derived primary lymphoma cells and cell lines as well as that they promote lymphoma cell proliferation and survival." (PMID 26636537, 2016). "Concomitant knockdown of PRDX1 and PRDX2 significantly attenuated the growth rate of lymphoma cells." (PMID 26636537, 2016). "Considering that TRX1 is already a known therapeutic target in lymphoma, we focused on two PRDX cytoplasmic isoforms, PRDX1 and PRDX2." (PMID 26636537, 2016). "Furthermore, in a model of BL cell lines, we show that concomitant downregulation of PRDX1 and PRDX2 diminishes the growth rate of lymphoma cells." (PMID 26636537, 2016). "A previous study indicated that the mice lacking PRDX1 have several malignant cancers, including sarcomas, carcinomas, and lymphomas." (PMID 25632391, 2015).
atherosclerosis (11 papers, 2013 to 2025). A disease characterized by the build-up of fatty material and calcium deposition in the arterial wall resulting in partial or complete occlusion of the arterial lumen. "By scavenging H2O2, Prdx1 suppresses the excessive activation of ECs and consequent vascular inflammation, while Prdx1 deficiency induces early atherosclerosis in ApoE‒/‒ mice." (PMID 34439492, 2021). "Previous studies found a protective effect of PRDX1 against endothelial hyperactivation and atherosclerosis." (PMID 37794518, 2023). "Cross-sectional studies showed that Prdx1 increased in chronic metabolic diseases (i.e., atherosclerosis, diabetes, etc.)." (PMID 36619535, 2022). "Atherosclerosis and chronic inflammation model mice (Prdx1−/−;ApoE−/−) show increased formation of atherosclerotic plaque compared with Prdx1+/+;ApoE−/− mice." (PMID 32098329, 2020). "PRDX1 is involved in tumor suppression, inflammation, apoptosis, atherosclerosis, and molecular chaperoning." (PMID 32098329, 2020). "SOD and Prdx-1 both are member of a ubiquitous family of antioxidant enzymes that reduces oxLDL levels and early atherosclerosis." (PMID 27536279, 2016). "Prdx1 (peroxiredoxin 1) deficiency in MØ leads to increased susceptibility to oxidative stress and impaired clearance of modified LDL due to defective lipophagic flux, thereby promoting atherosclerosis in apoE-deficient mice." (PMID 40607379, 2025). "Moreover, several members of the Prdx family (e.g., Prdx1, 2 and 6) contribute to antioxidative signalling and thereby to cascades that protect against atherosclerosis-prone and mechanically induced vessel pathophysiology." (PMID 35456043, 2022). "Moreover, another report suggested that lipophagy, the selective autophagic degradation of lipid in macrophages, is another possible protective role of Prdx1 in atherosclerosis." (PMID 34439492, 2021). "Nrf2-regulated genes such as heme oxygenase (decycling) 1 (HMOX1), peroxiredoxin (PRDX1), glutathione peroxidase 1 (GPX1), glutamate-cysteine ligase modifier subunit (GCLM) and NADPH quinine oxidoreductase 1 (NQO1) have been implicated in the protection against atherosclerosis and oxidative stress." (PMID 29113088, 2017). "Five of eight proteins are Peroxiredoxin-1 (Prdx-1), superoxide dismutase (SOD1), haemopexin (HPX), 60 kDa heat shock protein (HSP60), and serine/threonine-protein phosphatase (CPPED1), all of which are related to lipid peroxidation and atherosclerosis." (PMID 27536279, 2016). "Among the various antioxidant enzymes in macrophages, Prdx1 is highly expressed and is a major contributor to the maintenance of lipophagic flux and cholesterol homeostasis by regulating excessive H2O2 in macrophages and reducing foam cell formation and atherosclerosis." (PMID 34439492, 2021).
cervical carcinoma (11 papers, 2016 to 2024). A carcinoma arising from either the exocervical squamous epithelium or the endocervical glandular epithelium. "This intricate interplay between BLM, ROS, PRDX1 and 2, and the ER stress response reveals a complex mechanism underlying cervical cancer cell apoptosis, offering potential targets for therapeutic intervention." (PMID 38821929, 2024). "However, the detailed mechanism underlying PRDX1 overexpression in cervical cancer remains unclear and worthy of further study." (PMID 31956363, 2020). "SiHa cervical cancer cell lines were engineered with empty vectors, and specific knockdowns for PRDX1 and PRDX2 were created." (PMID 38821929, 2024). "Higher PRDX1 expression in tumors than in corresponding normal tissues has been observed in cervical carcinoma and Burkitt lymphoma." (PMID 36839749, 2023). "This study indicates that PRDX1 overexpression promotes proliferation and metastasis of cervical cancer." (PMID 31956363, 2020). "Until now, the change in PRDX1 expression during the process of cervical cancer carcinogenesis is unclear." (PMID 31956363, 2020). "In this study, the effect of PRDX1 expression on the proliferation and metastasis of cervical cancer was studied on SiHa cells." (PMID 31956363, 2020). "Our study, for the first time, showed that down-regulation of PRDX1 suppressed cervical cancer cell growth as demonstrated by the reduced growth speed and decreased the proportion of BrdU-positive cells compared with the control cells." (PMID 31956363, 2020). "Consistent with the previous findings, our study demonstrated that overexpression of PRDX1 significantly promotes cervical cancer cell proliferation, and enhanced the expression of Nanog, PCNA and Bcl-2 and decreased the expression of BAX." (PMID 31956363, 2020). "To further investigate the function of PRDX1 in cervical cancer progression, we used recombinant lentivirus to upregulate or downregulate the expression of PRDX1." (PMID 31956363, 2020). "Lentivirus containing PRDX1-cDNA or shRNA against PRDX1 was constructed to overexpress or knockdown PRDX1 in SiHa cervical cancer cells." (PMID 31956363, 2020). "To conclude, our study indicates that as an oncogene, PRDX1 is an important regulator of cervical cancer which facilitates tumor cell proliferation, migration and invasion and suppresses cellular apoptosis." (PMID 31956363, 2020). "The role of PRDX1 in promoting SiHa cervical cancer cell proliferation and inhibiting apoptosis has also been confirmed in vivo in a mouse xenograft model." (PMID 31956363, 2020). "In our study, PRDX1 was found to significantly promoted the migration and invasion of cervical cancer cells." (PMID 31956363, 2020). "In the present study, we found that upregulation or downregulation the expression of PRDX1 significantly promoted or suppressed the proliferation and colony formation of cervical cancer cells." (PMID 31956363, 2020). "They identified that oxidative stress-related proteins, such as receptor of activated protein kinase C 1 (RACK1), ras-related nuclear protein (RAN) and peroxiredoxin 1 (PRDX1), were IgG-interacting proteins in HeLa cells (cervical cancer)." (PMID 28536629, 2016). "While Keratin, type II cytoskeletal 5, Peroxiredoxin-1 and 14-3-3 protein sigma showed a decrease in their protein expression level in cervical cancer in comparison with normal cervix cells." (PMID 27601940, 2016). "This research highlights the importance of PRDX1 and 2 in cervical cancer treatments with bleomycin, showing their potential to enhance treatment efficacy by managing ROS and ER stress and suggesting a therapeutic strategy for improving outcomes in cervical cancer treatment." (PMID 38821929, 2024). "This strategy could potentially provide a more effective approach to combat cervical cancer, emphasizing the significant therapeutic potential of PRDX1 and PRDX2 modulation in conjunction with BLM treatment." (PMID 38821929, 2024).